IFITM3 (interferon induced transmembrane protein 3)
Diseases named in the same sentence as IFITM3 in open-access papers (continued):
Sharing a sentence is not in itself a finding about the gene and the disease.
infection (continued). "Quantification of virus colocalization with IFITM3-imNG over time shows that IAVpp increasingly co-localizes with IFITM3-imNG compartments, while LASVpp does not show a significant increase in colocalization up to 1 hr post-infection." (PMID 30640957, 2019). "Remarkably, IFITMdel mice did not experience more severe infections than IFITM3 KO mice, suggesting that other IFITMs do not contribute significantly to influenza virus resistance in vivo." (PMID 30662816, 2018). "In summary, in NPC1-inhibited A549 cells, through either AnxA6 expression or U18666A treatment, the cholesterol imbalance in the LE/L compartment restricted the first infection cycle of incoming IAV particles, independently of the antiviral properties of IFITM3." (PMID 30042202, 2018). "When cells overexpressing IFITM3 are challenged with IAV, productive infection is inhibited." (PMID 29162141, 2017). "Moreover, to establish the relationship of TCP and IFITM3, we used IFITM-knockout mice infected with sublethal infection of SC09 pandemic virus." (PMID 29281729, 2017). "Indeed, we observed that IFITM3 and ISG15 protein levels were greatly elevated in spleen, mesenteric lymph node, inguinal lymph node, and sub-maxillary node in pigs after the infection." (PMID 29312239, 2017). "Our data showed that the CC genotype of IFITM3 rs12252 was more frequent in severe infection cases rather than in mild cases." (PMID 28713779, 2017). "In light of the positive response of goose IFITM1 and IFITM3 to TMUV infection, we speculate that goose IFITM1 and IFITM3 might facilitate IFN-mediated defenses against TMUV." (PMID 28386554, 2017). "In order to measure the association between the IFITM3 rs12252 variant and influenza A(H1N1)pdm09 severity infection among ILI patients without reported comorbilities, we have designed a specific case-control study, in the H1N1 pandemic scenario." (PMID 27351739, 2016). "Instead, IFITM3 apparently increased the accumulation of virions that are probably retained and do not proceed to degradation and/or to a productive infection." (PMID 27116236, 2016). "Indeed, expression of one of these genes, Ifitm3, by TRM protects them from infection by the virus, as its invalidation leads to decreased protection against influenza infection." (PMID 27883012, 2016). "Components of interferon pathway and innate immunity (IFI44L, IFITM3, MX1, IRF7, OAS2, STAT2, etc.)are significantly upregulated in the acute phase of infection, while the expression levels of genes involved in translational elongation and protein biosynthesis are decreased." (PMID 26070066, 2015). "Although the attenuated effect of Δ21 IFITM3 and Y20A IFITM3 on H3 and H7(FPV) infections could be observed, this inhibition was still significant and even more prominent than the effect of FL IFITM3 on VSV entry." (PMID 25314048, 2014). "Following infection with two H5N1 strains of avian influenza virus (A/duck/Hubei/49/05 and A/goose/Hubei/65/05), levels of expression of duck IFITM3, -5, and -10 (measured by RNAseq) were increased to various degrees, reflecting a response befitting their expected function." (PMID 24067955, 2013). "Ifitm3 does not contribute to the infection phenotype of Citrobacter, Salmonella or Mycobacterium bacterial infections." (PMID 24278312, 2013). "As sufficient expression of IFITM3 effectively restricted infection by influenza virus, vesticular stomatitis virus, filoviruses, and SARS coronavirus, sufficient expression of IFITM3 might also be critical in reducing survival of M. tuberculosis." (PMID 23874452, 2013). "Similarly to its effect on H5-expressing pseudoparticles, IFITM3 inhibited replication of infectious avian H5N1 influenza A virus, A/Vietnam/1203/04 (VN/04), isolated from a fatal human infection." (PMID 22046135, 2011).
infection (continued). "IFITM3 does not appear to have functions in bacterial immunity but has been reported to promote infection by the intracellular pathogen Listeria monocytogenes; upregulation of this gene, therefore, is potentially a byproduct of strong type-I IFN signalling in low responders." (PMID 40826444, 2025). "In summary, IFITM3 KO mice: 1) permit replication of diverse non-adapted influenza viruses, 2) display increased viral burden allowing for more rigorous evaluation of vaccine efficacy, and 3) exhibit adaptive immune responses to infection and vaccination." (PMID 40501891, 2025). "The results showed that the expression of MAVS, IRF7, STING, NF-κB, MAD5, LGP2, IFN-α and IFN-β was upregulated compared with that in the control group, regardless of whether IFITM3 was overexpressed or inhibited after infection." (PMID 38543696, 2024). "Some studies examining seasonal influenza have not observed major impacts of the IFITM3 SNPs on infection severity, suggesting that pre-existing adaptive immunity may compensate for diminished IFITM3 activity in some circumstances." (PMID 39477971, 2024). "However, our human and mice analyses might indicate a direct influence of infection on the regulation of bulk IFITM1 and IFITM3 expression in vivo." (PMID 35708622, 2022). "Thus, our findings show that during nonviral infections, IFITM3 is upregulated in human megakaryocytes and platelets by IFN-dependent activation of transcriptional and translational pathways." (PMID 36194487, 2022). "Additionally, the HDV-1T and HDV-WHO infection rates were lower for the IFITM3 siRNA transfected cells but without reaching the level of significance." (PMID 35458456, 2022). "However, IFITM3 is mostly expressed in lung tissue-resident memory T cells (TRM), a cell population that ensures the first line of defense against pathogen re-encounter while being directly exposed to infection." (PMID 33810083, 2021). "In contrast, IFITM3(Y20A)-HA and IFITM3(Δ1-21)-HA failed to impair infection." (PMID 34078739, 2021). "In the case of SARS-CoV-2, it is therefore not inconceivable that if there is in fact a pro-infection role of IFITM3, that the virus could have evolved to exploit the most abundant haplotype A_C (59% abundance across all populations)." (PMID 33240681, 2020). "Importantly, we observed inconsistent effects by Vpr on IFITM3 expression; in four side-by-side infections with or without Vpr, we found that Vpr reduced IFITM3 expression is only one case." (PMID 32726944, 2020). "We previously showed that microbat IFITM3 retains sequence motifs for endocytosis and PTM, traffics to the plasma membrane before endocytic uptake, co-localizes with endosomal markers, and at normal expression levels in primary microbat cells, inhibits infection by pH-dependent enveloped viruses." (PMID 31826928, 2020). "A previous study showed that IFITM3 incorporated into HIV virions could effectively impair virion spread in target cells, and for PRRSV, intercellular transmission was an important means for establishment of sustained and effective infection." (PMID 32999030, 2020). "Alternatively, IFITM3 clusters may be abrogated once productive infection has occurred and may thus no longer be visible in these cells." (PMID 31212878, 2019). "In contrast, no such IFITM3 clusters were seen in productively infected A549 cells with a strong nuclear NP signal, and we speculate that infection of this cell type mainly occurs in cells that have not managed to block IAV entry by inducing IFITM3 clustering." (PMID 31212878, 2019). "In addition, IFITM3 promotes the survival of mouse lung-resident CD8+ T cells following IAV challenge, which may help clear the infection." (PMID 31574965, 2019). "IFITM3 may also provide a protective effect in certain infections independent of its inhibition of virus entry into cells." (PMID 30662816, 2018).
infection (continued). "However, we performed a similar experiment in 293T cell-derived lines and found an enhancement of infection in 293T cells following low-pH treatment of cell-binding virions in the presence or absence of IFITM3." (PMID 29503647, 2018). "It was reported that elevated levels of IFITM3 protein in memory CD8+ T lymphocytes, which kill virus-infected cells and serve as important targets themselves for IAV infection in the lung, promotes their survival during infection and enables long-term defense against future viral exposures." (PMID 29162141, 2017). "In addition, IFITM3-associated LSD1 levels did not decrease as fast as in IAV and VSV infections indicating that Zika virus did not disrupt LSD1/IFITM3 interaction as efficiently as VSV and IAV." (PMID 29281729, 2017). "Our previous study has unexpectedly shown that IFITM3 may not limit but rather promote the progression of DNA virus such as HCMV by facilitating the formation of the virion assembly compartment during infection in cell culture." (PMID 29281729, 2017). "Together with our previous findings that IAV or VSV infection increased the levels of IFITM3-K88me1 gradually upon infection, the data in all suggested that virus may develop strategies to comprise the action of type I IFN by inhibiting the binding of LSD1 to IFITM3." (PMID 29281729, 2017). "Indeed, it is likely that all DC gain increased resistance to infection by IAV and other viruses by activating IFITM3 expression, a property that would be beneficial not only to preserve their antigen-presenting function but also to prevent viral dissemination." (PMID 26600246, 2015). "One can therefore envision that IFITM3 may inhibit infection by redirecting viruses to a non-productive pathway, perhaps involving fusion with ILVs instead of the limiting membrane of LE (Pathway 3)." (PMID 24699674, 2014). "However, IFITM3’s role in other infections or the effect in removing IFITM3 in vivo in the absence of infection is not well understood." (PMID 24278312, 2013). "Ifitm3-/- mice appeared to gain proportional weight at a slower rate, however, this was due to these mice being on average 5g heavier at the start of challenge and based on lack of bacterial counts and pathology, is unlikely to be due to infection." (PMID 24278312, 2013). "Robust Ifitm3 expression was also observed in several tissues in the absence of infection." (PMID 22969429, 2012). "IFITM3 limits the severity of influenza virus infections in humans and mice, but whether it influences the minimum viral dose required for productive infection in vivo has not been tested." (PMID 39477971, 2024). "Interestingly, although IFITMdel mice were more susceptible to IAV infection than mice carrying intact IFITM gene locus, IFITMdel mice did not manifest more severe infections than IFITM3 KO mice, implying that the IFITM3 protein is critical in restricting IAV in mice." (PMID 38793616, 2024). "Similarly IFITM3 has been found to interact directly with IAV hemagglutinin (HA), while interactions between IFITM proteins and SARS-CoV-2 spike have also been described and may influence infection outcome." (PMID 36435199, 2023). "Finally, CHIKV and MAYV infection failed to modulate IFITM3 mRNA expression in HeLa cells, excluding that infection modulates transcription of the IFITM3 gene, and suggesting an infection-induced modulation of IFITM3 protein steady-state levels." (PMID 34078739, 2021). "To explore whether IFITM3 is active at earlier stages, we examined virus production at 24 h post-infection and the results were the same as what was observed at 48 h post-infection, suggesting that a transient effect of IFITM3 is not likely to explain differences in results among studies." (PMID 32370187, 2020).
infection (continued). "Overall, these results suggest that IFITM3 may possess a mechanistically uncharacterized ability to dampen IL-6 production [43•] and also that IFITM3 may play underappreciated roles in preventing cytokine-driven immunopathologies, even in infections that are not directly restricted by IFITM3." (PMID 30662816, 2018). "We further knocked down IFITM3 in TMPRSS2-positive Calu-3 cells, and did not observe any effect on infection of SARS-CoV-2 S-pseudotyped virus." (PMID 36423162, 2022). "The expression levels of IFITM3, ZFP313, DDIT4, and CD47 were rapidly upregulated in the early stage of infection, though not very highly." (PMID 33614762, 2021). "In both cases, statistical analysis indicated that infection by VSV-G pseudotypes was significantly different than HIV-1 wt either in the presence of IFNα or in untreated cells lacking IFITM2 and IFITM3." (PMID 29554922, 2018). "As such, NEDD4 KO cells accumulate high levels of basal IFITM3 even in the absence of IFN stimulation and are thus resistant to infection with IFITM3-sensitive viruses." (PMID 30662816, 2018). "We show that normal infection by both SFV and SINV is restricted by IFITM3 and, to a lesser extent, by IFITM2, but not by IFITM1." (PMID 27219333, 2016). "All three shIFITM3 cell lines showed increased infection (WSN/33 strain) and strong IFITM3 knockdown, when compared to the negative control cell line expressing a shRNA against firefly luciferase (shLuc), with or without IFN treatment." (PMID 22046135, 2011). "shRNA targeting IFITM3 markedly enhanced entry mediated by all four IAV HA proteins assayed, but did not substantially increase infection by MARV, EBOV, or control pseudoviruses." (PMID 21253575, 2011). "In the present study, we observed that several ISGs with known or proposed anti-CCHFV activity, i.e., Mx1, ISG15 and ISG20 or not defined for CCHFV like IFIT1, IFIT3, IFITM3, IFI16, and OAS3 were upregulated in the acute phase CCHFV patient samples as well as in the cell-infection model." (PMID 35437144, 2022). "No IFITM3 clustering at vesicular structures was observed in HSAEpCs in the absence of IAV infection, while the overall IFITM3 signal intensity was much higher in these primary cells compared to A549 cells without infection." (PMID 31212878, 2019). "UV inactivation of HBV abolishes the block in innate immune activation, as evident by the increased levels of IFI27 and IFITM3 mRNA in the absence of HBV replication 10 days postinfection, supporting that direct immune evasion of HBV occurs early during infection." (PMID 29445209, 2018). "The results showed that the infection of VTT in A549 cells was not accelerated by low pH, and had no affect the antiviral activity of IFITM3, indicating that VTT may enter A549 cells either through the plasma membrane or a neutral pH endocytic route." (PMID 29503647, 2018). "After infection, the expression of MAVS, IRF7, STING, NF-κB, MAD5, LGP2, IFN-α and IFN-β was upregulated compared with that in the control group, regardless of whether IFITM3 was overexpressed or inhibited." (PMID 38543696, 2024). "Furthermore, a mutant of IFITM3, which is localized to the plasma membrane (Y20A), inhibited infection by plasma membrane fusion more potently than IFITM1, but did not inhibit the endosomal route of infection." (PMID 27219333, 2016).
tumor (74 papers, 2008 to 2026). "In this T-cell-deficient model, tumor growth in IFITM3-overexpressing mice was comparable to that observed in the controls, indicating that the antitumor effects of IFITM3 overexpression are dependent on T-cell-mediated immunity." (PMID 40611157, 2025). "Here, we showed that IFITM3-deficient Tregs blunted tumor growth by strengthening the tumor-killing response and displayed the Th1-like Treg phenotype with higher secretion of IFNγ." (PMID 38167862, 2024). "Meanwhile, decreased suppressive cytokine IL10 and increased tumor-killing cytokine IFNγ expression were detected in IFITM3-deficient TI-Treg cells." (PMID 38167862, 2024). "According to recent research, IFITM3 expression levels are directly associated with tumor differentiation, lymph node, distant metastasis, and tumor node metastasis stages." (PMID 38791918, 2024). "Considering that IFITM3 participates in diverse signaling pathways that are likely to cause for oncogenesis and tumor development, it is deemed as a new therapeutic biomarker." (PMID 37304304, 2023). "Current knowledge of the molecular mechanism by which IFITM3 confers migration and metastasis benefits to tumor cells shows partial overlap with pathways linked to IFITM1." (PMID 36466909, 2022). "In contrast, the cyclin D1, CDK4 and pRB proteins are present at reduced levels that explain the observed cell cycle arrest in IFITM3-deficient tumor cells." (PMID 36466909, 2022). "Increased levels of the IFITM1, IFITM2, and IFITM3 proteins cause higher proliferation of tumor cells, facilitate migration and invasion and influence crosstalk between tumor and immune cells." (PMID 36466909, 2022). "IFIT1 and IFITM3 expression were related to several immune checkpoint molecules and tumor-associated macrophage markers." (PMID 35941292, 2022). "Considering that the IMvigor210 cohort contained information on PD-L1 expression in immune cells (ICs) and tumor cells (TCs), immunotypes of tumors, and response to immunotherapy, we next assessed the association between IFITM3 expression and these data." (PMID 34456915, 2021). "Knockdown of IFITM3 expression has reportedly caused suppression of cancer growth indicating its involvement in tumor progression." (PMID 34469466, 2021). "In UCEC and PRAD patients, the high expression of TMPRSS2 or low expression of IFITM3 in tumor tissues indicated a higher susceptibility to SARS-CoV-2 infection compared with the healthy individuals." (PMID 33061814, 2020). "Involvement of IFITM3 in these processes demonstrates its role in tumor associated antigen presentation and specific immune engagement for keeping tumor and immune system equilibrium." (PMID 33364194, 2020). "IFITM3 is highly expressed in many cancers and has been variously implicated in tumour cell proliferation, migration and invasion." (PMID 28362576, 2017). "Since IFITM3 was associated with tumor progression and its deficiency-induced instability of Treg cells, we hypothesized that IFITM3 was involved in regulating Treg cells in the TME." (PMID 38167862, 2024). "Collectively, these results indicate that IFITM3 is associated with tumor progression and may exert substantial roles in the regulation of TI-Treg cells." (PMID 38167862, 2024). "In addition to the expression level of IFITM3, T status of tumor (p = 0.008) was also elucidated to be associated with the lymphatic recurrence in pN0 ESCC." (PMID 26539332, 2015). "However, further experimental validation that directly evaluates the impact of IFITM3 loss in an immunocompetent mouse model can shed further light on the direct impact of IFNγ-IFITM3 axis mediated from the tumor immune microenvironment on therapeutic resistance in AML." (PMID 38418901, 2024). "In vitro and in vivo functional studies were conducted to evaluate the role and mechanisms of IFITM3 in modulating tumor sensitivity to PD-1 inhibitors." (PMID 40611157, 2025).